MUC16 (mucin 16, cell surface associated)
Diseases named in the same sentence as MUC16 in open-access papers (continued):
Sharing a sentence is not in itself a finding about the gene and the disease.
pancreatic cancer (90 papers, 2011 to 2025). "In highly metastatic pancreatic cancer, mutated KrasG12D induces upregulation of MUC16 by ERK/F-box and WD repeat dominium containing 7 (FBW7)/c-Myc axis." (PMID 38758220, 2024). "MUC16-mediated metabolic reprogramming in pancreatic cancer is associated with cellular invasion and motility." (PMID 36670203, 2023). "A regulatory linkage between dual-specificity phosphatase 28 (DUSP28) and MUC5B/MUC16 was reported in pancreatic cancer cells by a study to elucidate the underlying mechanism by which DUSP28 promotes the development of pancreatic cancer." (PMID 32695780, 2020). "We previously identified specific genes, MUC16 and mesothelin, associated with invasion and migration processes in pancreatic cancer." (PMID 30140382, 2018). "This study demonstrates the synthesis of a MUC16-targeted antibody–gadolinium magnetic resonance imaging (MRI) conjugate for pancreatic cancer." (PMID 40149293, 2025). "This study awas conducted to bring a humanized antibody to the clinic and use it in a “theranostic” sense for the high-resolution detection of MUC16-expressing pancreatic cancer lesions in patients." (PMID 40149293, 2025). "In this study, we describe the development of a MUC16-targeted antibody–MRI conjugate for detecting pancreatic cancer at different stages in preclinical models." (PMID 40149293, 2025). "In this study, we combine the spatial resolution advantage provided by MRI contrast imaging with a humanized targeted anti-MUC16 antibody to detect MUC16-expressing lesions of pancreatic cancer in mouse models." (PMID 40149293, 2025). "In conclusion, we report on the design and development of a novel MUC16-targeted antibody MRI probe to diagnose MUC16-expressing pancreatic cancer in the early stages with smaller lesions and under aggressive disease burden with sizable tumors." (PMID 40149293, 2025). "Pancreatic cancer has the fourth-highest percentage of patients whose tumors express Muc16, following the well-characterized gynecological cancers, including ovarian, cervical, and endometrial." (PMID 39346763, 2024). "Since then, it has been shown that Muc16 is an aberrant glycoprotein expressed by many solid tumors, such as ovarian, breast, lung, and pancreatic cancer." (PMID 39346763, 2024). "MUC16 was regarded to be an effective biomarker in the detection of pancreatic cancer, gastric cancer, and colorectal cancer." (PMID 39830210, 2024). "In fact, targeting other membrane-proximal epitopes of Muc16 with a chimeric antibody (ch5E6) has shown promising preclinical results in the setting of pancreatic cancer." (PMID 39346763, 2024). "MUC16 enhances pancreatic cancer cell invasion and migration by interacting with endothelin, thus playing a key role in the progression and worsening of PDAC." (PMID 38361923, 2024). "We establish clinically relevant, endogenous Muc16 and Muc16CD expression in pancreatic tumor tissues for CAR T cell targeting." (PMID 39346763, 2024). "Long-term survivors of pancreatic cancer have a high number of MUC16 neoantigens, much higher than short-term survivors, and MUC16 neoantigens can bind to T cells for specific T cell responses." (PMID 38758220, 2024). "MUC16/c-Myc forms a positive feedback loop in highly metastatic pancreatic cancer to maintain high serum CA125 levels." (PMID 38758220, 2024). "MUC16 has been expressed in a variety of cancers, such as pancreatic cancer, and can be used as a marker for pan-cancer." (PMID 38758220, 2024). "Of the five most used proteins in the BTC signatures (IL-6, IL-15, PTN, CCL23, and MUC-16), only IL-6 was used in the primary pancreatic cancer signatures." (PMID 36831406, 2023). "Compared to pancreatic normal tissues, the expression levels of MET, KRT7, and MUC16 were remarkably higher in pancreatic tumour tissues." (PMID 37815881, 2023).
pancreatic cancer (continued). "Our previous study has demonstrated that MUC16 promotes pancreatic cancer metastasis by activating the epithelial to mesenchymal phenotype through FAK activation." (PMID 36918912, 2023). "Meanwhile, recent studies have found that pancreatic cancer exhibits an overexpression of CA125 (MUC16)." (PMID 37670245, 2023). "Our study showed that MUC16 was significantly higher expressed in pancreatic tumour than normal pancreatic tissues and was related to a worse prognosis." (PMID 37815881, 2023). "Based on GEPIA database, we found that mRNA expression of MET, KRT7, and MUC16 was remarkably higher in pancreatic tumour than in normal tissues." (PMID 37815881, 2023). "By binding with mesenchymal cells, CA125/MUC16 can enhance the invasion and motility of pancreatic cancer cells, and knockout of MUC16 can reduce the growth and metastasis of pancreatic cancer." (PMID 37670245, 2023). "Large-scale genomic dataset analyses demonstrated that the synergistic effect of MUC4, MUC16, and MUC20 was linked to a statistically significant reduction in OS and elevated HR in colon, stomach, and pancreatic cancers." (PMID 36059804, 2022). "This study analyzed the relationship between the expression level of the mucin family and its subtypes (MUC1, MUC4, MUC5, MUC16) and the overall survival of patients with pancreatic cancer." (PMID 35709153, 2022). "Intriguingly, MUC16 has emerged as a potential target for novel cancer therapies using monoclonal antibodies or immunotherapy, particularly for ovarian and pancreatic cancer." (PMID 36230626, 2022). "Interestingly, these alterations also occur in pancreatic cancer, where they have been associated with disease progression and metastasis through the activation of oncogenic pathways via the interaction between aberrant MUC16 isoforms and epidermal growth factor (EGF) receptors." (PMID 35884534, 2022). "The meta-analysis demonstrated that the overall expression level of mucin and the expression levels of MUC4 and MUC16 were important prognostic predictors for pancreatic cancer patients." (PMID 35709153, 2022). "MUC16 also has a similar role in metabolic reprogramming in pancreatic cancer through the mTOR (mammalian target of rapamycin) and c-MYC pathways." (PMID 34681277, 2021). "MUC16 is also a mediator of EMT in pancreatic cancer, and its knockdown results in a decreased migration of cancer cells in vitro and reduced metastasis in vivo." (PMID 34681277, 2021). "It was discovered that MUC16 neoantigens were able to elicit CD8+ T cell response in long-term survivors of pancreatic cancers." (PMID 32664247, 2020). "Mucins, especially the highly-glycosylated MUC1, MUC4, MUC5AC, and MUC16, are prominently observed in pancreatic cancer and major carriers of glycans including the CA 19-9 antigen." (PMID 32582529, 2020). "In BxPC3, the presence of several types of mucins (MUC5AC, MUC5B, and MUC16) reflected what is described for pancreatic tumors, which are known to overexpress these proteins." (PMID 32886718, 2020). "We recently proposed the high expression of MUC4/MUC16/MUC20 signature as a marker of poor prognosis for pancreatic cancers." (PMID 33182511, 2020). "Apart from these, another MUC member, MUC1, which has a similar structure to MUC16, interacts with p120ctn to regulate the dynamic features of cell adhesion, motility and metastasis in pancreatic cancer." (PMID 30795761, 2019). "MUC16 is found to be overexpressed in various cancers including pancreatic carcinoma, breast cancer, non-small-cell lung cancer, and especially EOC." (PMID 30795761, 2019). "MUC16 has been reported to be an important factor in tumor diagnosis since it contains the CA125 cancer antigen which is strongly deregulated in pancreatic cancer." (PMID 29588543, 2018).
pancreatic cancer (continued). "Overall, we observed that MUC4/MUC16/MUC20 signature harbored an increased hazard ratio compared with MUC4 alone for pancreatic cancer and to a lower extent in bladder cancer, colon cancer, lung squamous cancer and stomach cancer." (PMID 30236127, 2018). "Pancreatic cancer cells express high levels of MUC1, MUC4 and MUC16 mRNAs that encode membrane-bound mucins." (PMID 28262838, 2017). "Elevated expression of MUC16 has been found in breast cancer and late stage and metastatic sites of pancreatic cancer." (PMID 29333154, 2017). "We thus believe that Meso64-TR3 will be widely applicable for the treatment of MUC16-positive malignancies, including ovarian, breast and pancreatic cancers." (PMID 27120790, 2016). "Expression of the 114 amino acid C-terminal form of MUC16 enhances the nuclear localization of JAK2 in pancreatic cancer cells to promote metastatic and stem-like properties." (PMID 27483328, 2016). "Elevation of MUC16 (CA125) is well studied in ovarian cancer, and recently expression of MUC16 has been implicated as a significant factor in pancreatic cancer." (PMID 27483328, 2016). "In summary, in this study we provide the first experimental evidence that MUC16 plays an important role in pancreatic tumor development and facilitates metastasis." (PMID 27382435, 2016). "Of note, and only following combination treatment, Meso64-TR3 selectively eliminated the MUC16-positive cells from a mixed population of HPAC pancreatic cancer cells." (PMID 27120790, 2016). "Overall, our results demonstrate that MUC16 plays an important role in metabolic reprogramming of pancreatic cancer cells by increasing glycolysis and enhancing motility and invasiveness." (PMID 26046375, 2015). "The MUC16-induced alterations in glycolytic and nucleotide metabolism in culture models overlap with that of the human pancreatic tumor specimens, indicating the broader applicability of our findings to human pancreatic cancer." (PMID 26046375, 2015). "Because growth and invasive properties of most cancer cells significantly depend on their glycolytic capacity, we investigated the effect of MUC16 knockdown on glucose uptake of pancreatic cancer cells." (PMID 26046375, 2015). "Approximately 85–95% of PC patients are diagnosed with either locally advanced or metastatic disease and a previous study from our lab demonstrated that MUC16 expression is much stronger in metastatic lesions compared to the primary pancreatic tumor." (PMID 25691062, 2015). "Our mass spectrometery-based metabolomics study of MUC16 knockdown pancreatic cancer cells indicates that MUC16 enhances glucose and nucleotide metabolism in pancreatic cancer cells." (PMID 26046375, 2015). "In the present study we characterized the metabolic changes induced by MUC16 in pancreatic cancer cells and investigated the role of such metabolic alterations in modulating MUC16-induced motility and invasiveness." (PMID 26046375, 2015). "Keeping in view the oncogenic functions of MUC16, we investigated its role in metabolic reprogramming of pancreatic cancer cells." (PMID 26046375, 2015). "MUC16 is significantly upregulated in pancreatic cancer and co-overexpressed with MSLN (Mesothelin) at the invading edge." (PMID 26555578, 2015). "Overall, these findings demonstrate an important role of MUC16 in metabolic reprogramming in pancreatic cancer." (PMID 26046375, 2015). "Overall, our results demonstrate that MUC16 enhances glycolytic gene expression and the glycolytic property of pancreatic cancer cells." (PMID 26046375, 2015). "To study the role of MUC16 on different metabolic properties of pancreatic cancer cells, we established Capan1-Scr, Capan1-shMUC16, Colo357-Scr and Colo357-shMUC16 cells." (PMID 26046375, 2015). "Our results demonstrate down-regulation of glycolytic genes as well as reduced activation of Akt and mTORC1, which can regulate c-MYC expression, in MUC16 knockdown pancreatic cancer cells." (PMID 26046375, 2015).
pancreatic cancer (continued). "Overall, these results suggest that MUC16 knockdown in pancreatic cancer cells leads to decreased Akt and mTORC1 activation and reduced protein synthesis and cell size." (PMID 26046375, 2015). "We then determined c-MYC status in the pancreatic cancer tissue specimens by immunohistochemistry and evaluated if MUC16 levels correlate with c-MYC levels." (PMID 26046375, 2015). "Our results demonstrate that MUC16 knockdown reduces expression of key glycolytic genes and glycolytic activity of the pancreatic cancer cells." (PMID 26046375, 2015). "Our LC-MS/MS based metabolomics studies indicate global metabolic alterations in MUC16 knockdown pancreatic cancer cells, as compared to the controls." (PMID 26046375, 2015). "Ectopic expression of c-MYC in MUC16 knockdown pancreatic cancer cells restores the altered cellular physiology." (PMID 26046375, 2015). "MUC16 expression is upregulated in pancreatic cancer, with strong upregulation in metastatic lesions." (PMID 26046375, 2015). "We are currently in the process of expanding our preclinical xenograft models to primary, MUC16-expressing human malignancies including ovarian and pancreatic cancers." (PMID 24447304, 2014). "Several studies have shown that aberrant and increased expression of MUC4 and MUC16 occurs during pancreatic cancer progression to metastasis." (PMID 24204560, 2013). "The transmembrane mucins, MUC4 and MUC16, are aberrantly overexpressed in many adenocarcinomas, including human pancreatic cancer." (PMID 24204560, 2013). "Increased expression of MUC16 is also observed in human pancreatic cancer, and we have recently shown that there is increased expression in metastatic lesions of pancreatic cancer patients." (PMID 24204560, 2013). "This suggests that pancreatic tumors maintain MUC16 expression during their spread, possibly pointing to the role of MUC16 in PC cell dissemination." (PMID 22066010, 2011). "The most common protein carriers of CA19-9 antigen in pancreatic cancer are MUC16, MUC1 and MUC5AC." (PMID 39863644, 2025). "As the designed conjugate is particular to MUC16 expressed in pancreatic cancer, it restricts its distribution and/or prolonged exposure to other tissues, thereby mitigating any off-target toxicity and false-positive images of normal tissue proximal to the pancreas." (PMID 40149293, 2025). "This shorter relaxation time in the in vitro assay strongly suggests that MUC16-targeted huAR9.6–Gd–DTPA could aid in detecting MUC16-bearing pancreatic cancer cells and lesions." (PMID 40149293, 2025). "Meanwhile, MUC16 can also activate c-Myc in pancreatic cancer, up-regulate the expression of c-Myc, enhance the binding of c-Myc to E-box in the promoter of microRNA-29a (miR-29a) (which is the downstream target of FBW7 gene), and inhibit the transcription of miR-29a." (PMID 38758220, 2024). "Additionally, the role of MUC1 and MUC16 in pancreatic cancer progression has been extensively validated." (PMID 38361923, 2024). "highlighted the role of MUC1 and MUC16 in breast and pancreatic cancer cells, showing that reducing their expression through COSMC gene knockdown enhances tumor cell sensitivity to natural killer cell-mediated antibody-dependent cellular cytotoxicity (ADCC) and cytotoxic T lymphocyte (CTL) killing." (PMID 38361923, 2024). "We first evaluated the clinical relevance of targeting Muc16 in resectable pancreatic cancer." (PMID 39346763, 2024). "MUC16 is overexpressed in pancreatic cancer, although hardly expressed in normal pancreatic ducts." (PMID 38758220, 2024). "Furthermore, MUC16 expression was found in precancerous lesions of pancreatic cancer, intraductal papillary mucinous neoplasms (IPMN), and pancreatic intraepithelial neoplasms (PanIN)." (PMID 39456534, 2024).
pancreatic cancer (continued). "CA 125, also known as mucin 16 (MUC16), has been recommended by the Chinese Study Group for Pancreatic Cancer for diagnosis, especially in conditions where the CA 19-9 levels are negative and can be used as an additional workup for CA 19-9, especially in hyperbilirubinemia conditions." (PMID 35611029, 2022). "The results showed that the overall expression level of mucin family and the patients with positive or high expression of MUC4 and MUC16 had a poor prognosis, indicating that mucin family can be used as a potential biomolecule to predict the prognosis of patients with pancreatic cancer." (PMID 35709153, 2022). "Indeed, substantial expressions of TF antigen are seen on mucin protein MUC1, MUC4, and MUC16 in colon, breast, and pancreatic cancer than in their normal counterparts." (PMID 34944925, 2021). "Besides CRC, other cancers were also predicted to produce a higher number of neoantigens towards the MUC16 gene such as gastric cancer and pancreatic cancer." (PMID 32664247, 2020). "Binding of mesothelin to MUC16 markedly enhances pancreatic cancer cell motility and invasion through selective induction of MMP-7 (one of the molecules most highly expressed in IPF compared to normal lung tissues or those from other ILDs) via a p38 MAPK-dependent pathway." (PMID 31514468, 2019). "Forced expression of a 17 kDa MUC16-Cter fragment in pancreatic cancer cells mediated nuclear translocation of JAK2 which preferentially phosphorylated tyrosine 41 of histone H3 (H3Y41) in a STAT-independent manner and up regulated stemness specific genes LMO2 and NANOG." (PMID 29682172, 2018). "Furthermore, high expression of mesothelin was correlated with poor prognosis in several human cancers, and in pancreatic cancer, the coexpression of MUC16 and mesothelin was reported to be an independent prognostic factor for poor prognosis." (PMID 30140382, 2018). "As expected, in the pancreatic tumor, MUC16 colocalizes with galectin-3." (PMID 27382435, 2016). "We observed reduced lactate secretion in MUC16 knockdown pancreatic cancer cells." (PMID 26046375, 2015). "In the current studies, we observed that MUC16 knockdown pancreatic cancer cells exhibit reduced glucose uptake and lactate secretion along with reduced migration and invasion potential, which can be restored by supplementing the culture media with lactate, an end product of aerobic glycolysis." (PMID 26046375, 2015). "Based on the overall metabolite profiles, control and MUC16 knockdown cultured cells, as well as MUC16-high and MUC16-low human pancreatic tumors, segregated in distinct clusters, in a MUC16 expression-dependent manner, in the respective 2D-PLS-DA (partial least squares discriminant analysis) plots." (PMID 26046375, 2015). "Furthermore, our metabolomics studies utilizing human pancreatic tumor specimens also indicate alterations in nucleotide intermediates and differential overall metabolite profiles, in a MUC16 expression-dependent manner." (PMID 26046375, 2015). "Furthermore, we analyzed the mRNA level of c-MYC in MUC16-high and MUC16-low human pancreatic cancer tissue specimens." (PMID 26046375, 2015). "Inflammatory stimuli such as oxidative stress and treatment with cytokines IFNγ, IL-1α, TNFα have also been found to alter the glycosylation pattern of MUC16 in pancreatic cancer cells, suggesting that MUC16 may play a key role in promoting inflammatory signaling in cancer." (PMID 38361923, 2024). "Interestingly, we also found that MUC4EGF1+2 regulates the expression of other membrane-bound mucins such as MUC1 and MUC16, two membrane-bound mucins that we recently described as being a potent molecular signature for bad prognosis in pancreatic cancer and overall survival." (PMID 34830899, 2021). "Furthermore, MUC16 expression correlates with the recurrence rate in pancreatic cancer." (PMID 26046375, 2015).